MSANTD5 (Myb/SANT DNA binding domain containing 5)
Gene: Protein-coding gene on chromosome 5 (178,694,572 to 178,697,761, reverse strand). Ensembl gene ENSG00000285891.
Homologues: Orthologues: macaque MSANTD5 (83% identical), pig MSANTD5 (53% identical), rat Msantd5l1 (36% identical), mouse Msantd5 (34% identical), mouse Msantd5l (33% identical), mouse Msantd5f6 (26% identical), mouse Gm38423 (25% identical), mouse Msantd5f1 (25% identical), mouse Msantd5f2 (25% identical), mouse Msantd5f3 (25% identical), mouse Msantd5f4 (25% identical), mouse Msantd5f5 (25% identical), and 5 more.